ACAA2 (acetyl-CoA acyltransferase 2)
Description:
In the production of energy from fats, this is one of the enzymes that catalyzes the last step of the mitochondrial beta-oxidation pathway, an aerobic process breaking down fatty acids into acetyl-CoA (Probable). Using free coenzyme A/CoA, catalyzes the thiolytic cleavage of medium- to long-chain unbranched 3-oxoacyl-CoAs into acetyl-CoA and a fatty acyl-CoA shortened by two carbon atoms (Probable). Also catalyzes the condensation of two acetyl-CoA molecules into acetoacetyl-CoA and could be involved in the production of ketone bodies (Probable). Also displays hydrolase activity on various fatty acyl-CoAs. Thereby, could be responsible for the production of acetate in a side reaction to beta-oxidation (Probable). Abolishes BNIP3-mediated apoptosis and mitochondrial damage.
Synonyms: DSAEC; T1
Tractability: Small molecule: a structure with a bound ligand is known. PROTAC: ubiquitination databases record sites on it; its protein half-life has been measured.
Target class: Enzyme; Transferase
Gene: Protein-coding gene on chromosome 18 (49,782,164 to 49,813,953, reverse strand). Ensembl gene ENSG00000167315.
Subcellular location: Mitochondrion
Subcellular location (Human Protein Atlas): Mitochondria; Basal body; Cytosol
Pathways (Reactome):
Metabolism: Mitochondrial Fatty Acid Beta-Oxidation
Gene Ontology:
Molecular function: acetyl-CoA C-acetyltransferase activity; acetyl-CoA C-acyltransferase activity; acetyl-CoA hydrolase activity; fatty acyl-CoA hydrolase activity; protein binding; RNA binding; acyltransferase activity; acyltransferase activity, transferring groups other than amino-acyl groups; long-chain fatty acyl-CoA hydrolase activity; medium-chain fatty acyl-CoA hydrolase activity; short-chain fatty acyl-CoA hydrolase activity
Biological process: cellular response to hypoxia; negative regulation of mitochondrial membrane permeability involved in apoptotic process; negative regulation of mitochondrial outer membrane permeabilization involved in apoptotic signaling pathway; cholesterol biosynthetic process; fatty acid beta-oxidation
Cellular component: mitochondrion; mitochondrial matrix
Genetic constraint (gnomAD): Loss-of-function variants: 30 observed, 35.45 expected, observed/expected ratio (o/e) 0.85, 90% interval 0.63 to 1.15. The upper end of that interval is the gene's LOEUF score, 1.15, which puts it in group 5 of 6, group 1 being the genes least tolerant of losing a copy. Missense variants: 404 observed, 426.92 expected, observed/expected ratio (o/e) 0.95, 90% interval 0.87 to 1.03. Synonymous variants: 127 observed, 151.26 expected, observed/expected ratio (o/e) 0.84, 90% interval 0.73 to 0.97.
Homologues: Orthologues: chimpanzee ACAA2 (99% identical), macaque ACAA2 (98% identical), pig ACAA2 (91% identical), guinea pig ACAA2 (90% identical), rabbit ACAA2 (90% identical), dog ACAA2 (88% identical), mouse Acaa2 (88% identical), rat Acaa2 (87% identical), zebrafish acaa2 (77% identical), tropical clawed frog acaa2 (74% identical), Drosophila melanogaster yip2 (59% identical), Caenorhabditis elegans acaa-2 (56% identical). Paralogues in human: ACAT2 (43% identical), ACAT1 (41% identical), ACAA1 (40% identical), HADHB (35% identical).
Diseases named in the same sentence as ACAA2 in open-access papers:
ACAA2 is named in the same sentence as 75 diseases in open-access papers, as found by Europe PMC text mining. Sharing a sentence is not in itself a finding about the gene and the disease. The quoted sentences say what the papers report.
breast carcinoma (5 papers, 2015 to 2024). "Low expression of ACAA2 was correlated with low overall survival rates in patients with cancer, including breast cancer, ovarian cancer and lung cancer and acted as a tumor suppressor." (PMID 36162992, 2022).
glioma (4 papers, 2020 to 2023). A benign or malignant brain and spinal cord tumor that arises from glial cells (astrocytes, oligodendrocytes, ependymal cells). "In this study, we identified ACAA2 as a prognostic factor in IDH mutation lower grade glioma with the method of weighted correlation network analysis (WGCNA)." (PMID 32280672, 2020). "When compared to glioma, ACAA2 expression level in neuroblastoma was significantly elevated (P = 2.5*10-6)." (PMID 37798372, 2023). "In the study, decreased ACAA2 expression and 169 downregulated lysine acetylation sites of 134 proteins were detected in glioma with seizures." (PMID 34664012, 2021). "The expression of ACAA2 in IDH wild-type glioma was significantly higher than that in IDH mutant glioma, while participating in fatty acid beta." (PMID 32280672, 2020). "The expression of ACAA2 in IDH1 wild-type glioma was significantly higher than that in IDH1 mutant glioma, while participating in fatty acid beta." (PMID 32280672, 2020). "Upregulated ACAT2 may contribute to elevated acetylation in glioma with seizures, while downregulated ACAA2 may contribute to reduced acetylation." (PMID 34664012, 2021). "ACAT2 and ACAA2 were the differentially regulated enzymes in glioma with seizure." (PMID 34664012, 2021). "However, even though we found some evidence which proved a clear relationship between ACAA2 and metabolism in the biological process of glioma, experiments in a molecular level were still needed." (PMID 32280672, 2020). "And among these genes, ACAA2, a crucial factor which regulates lipid acid beta oxidation, might have a vital role in the complex mechanism of metabolism processes in gliomas and might also be a new potential target for gliomas' comprehensive treatment." (PMID 32280672, 2020). "However, ACAA2 expression and function in glioma with seizures remain unclear." (PMID 34664012, 2021). "On the basis of clinical risk factors, we created a new classification and divided lower grade gliomas into IDH1-WT, IDH1-MUT and ACAA2 high, and IDH1-MUT and ACAA2 low types." (PMID 32280672, 2020). "The expression of fatty acid beta oxidation-related enzyme ACAA2 was significantly different between the IDH mutant and IDH wild-type gliomas." (PMID 32280672, 2020). "We also assessed ACAA2 mRNA levels in CCLE to demonstrate that ACAA2 mRNA expression is also significantly increased in SCLC (N = 50) and neuroblastoma cell lines (N = 16), both of which are NE cancers, relative to their non-NE counterparts: NSCLC (N = 120) and glioma (N = 53)." (PMID 37798372, 2023).
Obesity (4 papers, 2020 to 2024). Accumulation of substantial excess body fat. "Although the direct association between ACAA2 and bone metabolism remains unclear, its role in fatty acid oxidation suggests potential connections with metabolic diseases, such as obesity and diabetes." (PMID 39130750, 2024). "When looking at the fatty acid metabolism in obesity and uterine cancer, three miRNA-gene interactions (miR100/ALDH9A1, miR-186/ACAA2 and miR- 193b/ALDH3A2) were shared in common." (PMID 33121472, 2020). "ACAA2 and ACAD8 are proteins mainly catalyze dehydrogenation steps of β-oxidation processes in mitochondrial fatty acids catabolism, HIBCH involving in energy metabolism by regulating fat hydrolysis in obesity mice." (PMID 32053710, 2020).
heart failure (3 papers, 2016 to 2024). Inability of the heart to pump blood at an adequate rate to meet tissue metabolic requirements. "The expressions of ACADM, FABP3, ECH1, ACAA2, EHHADH and CPT1A in the left atria were significantly up-regulated in the MR patients with heart failure compared to patients with aortic valve disease and heart failure and normal controls." (PMID 27250500, 2016).
lung carcinoma (3 papers, 2021 to 2023). "The elevation of ACAA2 in NE lung cancers was further confirmed in the contingency plot of intensity scores." (PMID 37798372, 2023). "The correlation between ACAA2 and the SCNC phenotype was further confirmed via ACAA2 mRNA level analysis in two independent lung cancer patient datasets." (PMID 37798372, 2023). "ACAA2 expressions in tumour xenografts, tissue microarrays (TMAs), and patient tissues from prostate and lung cancers were analysed via immunohistochemistry." (PMID 37798372, 2023). "We discovered that ACAA2 expression is lower in lung cancer patients who were exposed to platinum-based therapy relative to non-treated patients, and that increased ACAA2 was associated with worse overall survival in lung adenocarcinoma (P = 2.2*10-4) and neuroblastoma patients (P = 2.77*10-2)." (PMID 37798372, 2023). "ACAA2 was also elevated in lung cancer patient tissues with neuroendocrine phenotype." (PMID 37798372, 2023). "Our study demonstrates that ACAA2 expression is elevated in cancers with NE phenotype through assessing the expression profile of ACAA2 in cell lines and xenografts of neuroblastoma as well as cell lines, xenografts, patient mRNA, and patient tissue samples from prostate and lung cancers." (PMID 37798372, 2023).
steatosis (3 papers, 2014 to 2022). Increased lipid within the cytoplasm of cells. "In particular, alterations in the expression of PPARα target genes involved in lipid catabolism (e.g. carnitine palmityltransferase 1 (Cpt1), 3-ketoacyl-CoA thiolase (Hadhb), acetyl-Coenzyme A acyltransferase 2 (Acaa2)), have been linked to the development of drug-induced steatosis." (PMID 24489787, 2014).
Hypoglycemia (2 papers, 2017 to 2025). A decreased concentration of glucose in the blood. "We report a novel variant in ACAA2 that causes hepatitis and hypoglycemia during infancy and lipodystrophy during adulthood accompanied by elevated plasma long chain acylcarnitines." (PMID 41186989, 2025). "Here, we report a heterozygous variant in the gene encoding acetyl-coenzyme A acyltransferase 2 (ACAA2), a mitochondrial fatty acid β-oxidation (mFAO) enzyme, in 4 families with FPL, lipomatosis, and variable occurrence of infantile steatohepatitis and hypoglycemia (IHH)." (PMID 41186989, 2025). "It will be interesting to investigate if the expression of the genes encoding MCKAT (ACAA2) or its inhibitor SHC1 might differentiate between MCAD-deficient patients that presented with hypoketotic hypoglycemia and those that never did." (PMID 28369071, 2017).
lipid metabolism disorder (2 papers, 2021 to 2024). "Some research has shown ACAA2 to affect meat quality, fatty acid metabolism, and lipid metabolism disorders." (PMID 33936163, 2021).
type 2 diabetes (2 papers, 2016 to 2024). "Research indicates that ACAA2 expression levels are correlated with the rate of glycolysis and are significant in type 2 diabetes progression." (PMID 39130750, 2024).
acute kidney injury (1 paper, 2025). Sudden and sustained deterioration of the kidney function characterized by decreased glomerular filtration rate, increased serum creatinine or oliguria. "The reduced expression of ACAA2 impaired fatty acid β-oxidation and eventually exacerbated kidney fibrosis in acute kidney injury." (PMID 40281739, 2025).
angina pectoris (1 paper, 2023). The symptom of paroxysmal pain consequent to MYOCARDIAL ISCHEMIA usually of distinctive character, location and radiation. "Currently, there is a pharmacological ACAA2 inhibitor, trimetazidine hydrochloride, that is currently used to treat angina pectoris and myocardial ischaemia as an anti-ischaemic (anti-anginal) metabolic agent in Europe." (PMID 37798372, 2023).
aortic valve disease (1 paper, 2016). "Notably, only ACADM, FABP3, ECH1, ACAA2, EHHADH, CPT1A and PLTP of the PPAR pathway were significantly differentially expressed in the MR patients compared to patients with aortic valve disease and normal controls." (PMID 27250500, 2016). "Notably, seven genes (ACADM, FABP3, ECH1, ACAA2, EHHADH, CPT1A and PLTP) of the PPAR signaling pathway were differentially expressed in the left atria of MR patients compared to patients with aortic valve disease and normal controls." (PMID 27250500, 2016). "Notably, only ACADM, FABP3, ECH1, ACAA2, EHHADH, CPT1A and PLTP of the PPAR signaling pathway were differentially expressed in the left atria of MR patients compared to patients with aortic valve disease and normal controls." (PMID 27250500, 2016).
cardiac hypertrophy (1 paper, 2020). "Fatty acid oxidation (Acadm, Etfdh, Acadl, Acadvl, Eci1, Hadh, Phyh, Acaa2, Hadha, Hadhb, Cd36), glucose metabolism (Dld, Pdha1, Pgam1, Pgam2, Acss1, Ldhb, Fh1, Slc2a4, Aldh6a1), TCA cycle (Aco2, Dld, Fh1, Ogdh, Sucla2, Sdha, Idh3b, Idh2) were up-regulated by hispidulin in cardiac hypertrophy." (PMID 33324687, 2020).
cholestasis (1 paper, 2018). Impairment of the bile flow caused by obstruction within the liver, or outside the liver in the bile duct system. "Mass spectrometric analysis of serum samples after cholestasis revealed upregulation of various proteins such as Lactate dehydrogenase (LDH), Betaine—homocysteine S-methyl transferase (BMHT), 3-Ketoacyl-CoA thiolase (ACAA2) and GRP78." (PMID 30111770, 2018).
coronary artery disease (1 paper, 2018). "ACAA2 is associated with abnormal blood lipid levels and an individual’s risk for coronary artery disease." (PMID 29310583, 2018).
diabetic retinopathy (1 paper, 2022). "For example, genes such as Aldh1a3, Cyp26b1 and Acaa2, without reference regarding anti-diabetic retinopathy function, would be the candidates for our future exploration." (PMID 36557283, 2022).
dilated cardiomyopathy (1 paper, 2015). Cardiomyopathy which is characterized by dilation and contractile dysfunction of the left and right ventricles. "Downregulated canonical pathways included those involved in arrhythmogenic, hypertrophic, and dilated cardiomyopathy signaling (e.g., Itgb6, Cacna1s, and Hadh), fatty acid metabolism, and peroxisome proliferator-activated receptor (PPAR) signaling (e.g., Acaa2, Cpt2, and Acsl6)." (PMID 25744495, 2015).
familial hypertrophic cardiomyopathy (1 paper, 2020). Hypertrophic cardiomyopathy caused by mutations in the genes encoding components of the sarcomere, in the absence of predisposing conditions. "Human genome-wide association studies (GWAS) have indicated that mutations in HADHA and HADHB are associated with familial hypertrophic cardiomyopathy, and mutations in CPT1, ACADM, and ACAA2 genes are associated with impaired mitochondrial fatty acid β-oxidation." (PMID 32804947, 2020).
fatty acid metabolism disorder (1 paper, 2025). "Therefore, abnormalities of Acads and Acaa2 may be the main reason for fatty acid metabolism disorder in the myocardial tissue of HOCM mice and may be associated with the occurrence of fibrosis, which is one of the most significant changes in HCM patients, especially in patients with HOCM." (PMID 40281739, 2025).
Hepatic fibrosis (1 paper, 2026). The presence of excessive fibrous connective tissue in the liver. "Here, we show that ACAA2 upregulation in HSCs exacerbates hepatic fibrosis by promoting ferroptosis-associated transcriptional programs, whereas ACAA2 inhibition attenuates both ferroptosis and fibrogenesis in preclinical models." (PMID 41564793, 2026). "Our study establishes ACAA2 palmitoylation as a druggable node for antifibrotic therapy, offering novel insights into metabolic regulation of hepatic fibrosis." (PMID 41564793, 2026).
Hepatic steatosis (1 paper, 2025). Steatosis is a term used to denote lipid accumulation within hepatocytes. "CYN promotes hepatic steatosis by elevating proteins involved in lipid metabolism (acetyl-CoA carboxylase, stearoyl-CoA desaturase-1, prosaposin, and ACAA2 (3-ketoacyl-CoA thiolase mitochondrial)) and potentially impairing autophagy." (PMID 41227594, 2025).
hyperthyroidism (1 paper, 2020). Overactivity of the thyroid gland resulting in overproduction of thyroid hormone and increased metabolic rate. "We found that hyperthyroidism decreased ACAA2 in aged hearts only in males." (PMID 33372611, 2020).
kidney tumor (1 paper, 2023). "The other 3 genes in the prognosis model associated with lipid metabolism regulation displayed the diagnostic potential to discriminate between normal and kidney tumor tissues: ACAT1, ANGPTL4 and ACAA2." (PMID 36829161, 2023). "Using IHC data from the Protein atlas database, we observed strong or moderate staining for ACAA2, ACAT1, ASRGL1, and AKR1B10, weak staining for ANGPTL4 and ABCC2 in normal kidney tissues and opposite staining results in kidney tumor samples." (PMID 36829161, 2023).
leukemia (1 paper, 2016). A malignant (clonal) hematologic disorder, involving hematopoietic stem cells and characterized by the presence of primitive or atypical myeloid or lymphoid cells in the bone marrow and the blood. "Acaa2 was reported to be differentially expressed in CEM and drug-resistant leukemia cells." (PMID 27809262, 2016).
liposarcoma (1 paper, 2007). A usually painless malignant tumor that arises from adipose tissue. "In addition, genes involved in receptor activity, signaling and lipid metabolism (some of which have previously been reported in liposarcoma) such as ACAA2, ARSA, DHRS3, PDE3A, and PPARA, were upregulated." (PMID 17359542, 2007).
lung adenocarcinoma (1 paper, 2023). A carcinoma that arises from the lung and is characterized by the presence of malignant glandular epithelial cells. "SCLC exhibited significantly elevated ACAA2 mRNA expressions when compared to lung adenocarcinoma [P = 2.52*10-5; 7.2*10-7] and normal lung tissues (P = 2.2*10-4), which further suggests a positive correlation between ACAA2 expression and SCNCs." (PMID 37798372, 2023).
lung carcinoid tumour (1 paper, 2023). "Using a 0 to 3 intensity scale, we discovered an increase of ACAA2 expression in lung carcinoid (P = 0.033) and SCLC (P = 0.034), relative to the non-NE, adenocarcinoma patient samples." (PMID 37798372, 2023).
lung disease (1 paper, 2014). "Ramp2 [Receptor (calcitonin) activity modifying protein 2], Acaa2 (Acetyl-Coenzyme A acyltransferase 2), Mdh1 (Malate dehydrogenase 1, NAD), and Tspan8 (Tetraspanin 8) are enriched mRNAs in the lungs and are involved in lung disease." (PMID 25070658, 2014).
metastatic prostate carcinoma (1 paper, 2023). A carcinoma that arises from the prostate gland and has spread to other anatomic sites. "In addition, our study suggests the role of ACAA2 in prostate cancer disease progression and its potential as a therapeutic target for advanced, metastatic prostate cancers." (PMID 37798372, 2023).
neuroblastoma (1 paper, 2023). Neuroblastoma (NB) is the most common solid, extracranial childhood tumor. "We identified that ACAA2 protein expression is also elevated in NE cell lines IMR32 (neuroblastoma), H82 (SCLC), and H29 (SCLC) measured by WB." (PMID 37798372, 2023). "Then, IHC was performed on neuroblastoma, SCLC, and NSCLC tumour xenografts and demonstrated enhanced expression of ACAA2 in neuroblastoma and SCLC relative to NSCLC." (PMID 37798372, 2023).
non-alcoholic fatty liver (1 paper, 2026). A benign form of fatty non-alcoholic fatty liver disease where the disease has not yet progressed to the inflammation of liver. "Two genes, ACAA2 and PLIN2, were significantly altered at both the transcript and protein levels and may be crucial for maintaining mitochondrial function in early non-alcoholic fatty liver (NAFL)." (PMID 41654732, 2026).
non-small cell lung carcinoma (1 paper, 2023). A group of at least three distinct histological types of lung cancer, including non-small cell squamous cell carcinoma, adenocarcinoma, and large cell carcinoma. "All non-small-cell lung cancer (NSCLC) cell lines, including H1650 and H358, exhibited undetectable levels of ACAA2 by WB." (PMID 37798372, 2023).
nonalcoholic steatohepatitis (1 paper, 2022). "Furthermore, nonalcoholic steatohepatitis (NASH) related differential lncRNAs were associated with predicted protein-coding targets of ACAA2." (PMID 36162992, 2022).
osteoporosis (1 paper, 2024). A condition of reduced bone mass, with decreased cortical thickness and a decrease in the number and size of the trabeculae of cancellous bone (but normal chemical composition), resulting in increased fracture incidence. "To address these deficiencies, we intend to conduct animal studies to enhance the reliability of the biomarkers and will continue monitoring the progress of ACAA2, DAP3, and BIK in relation to osteoporosis." (PMID 39130750, 2024).